IL10 (interleukin 10)
Diseases named in the same sentence as IL10 in open-access papers (continued):
Sharing a sentence is not in itself a finding about the gene and the disease.
Hashimoto thyroiditis (15 papers, 2015 to 2025). An autoimmune disorder caused by the production of autoantibodies against thyroid tissue. "In clinical studies, XYSJW has demonstrated a significant ability to reduce the levels of IFN-γ, IL-2, and IL-6 while increasing IL-10 levels in patients with Hashimoto’s thyroiditis and chronic lymphocytic thyroiditis, thereby regulating the Th1/Th2 balance." (PMID 40584613, 2025). "Elevated IL-10 levels were also found in individuals with Hashimoto’s thyroiditis compared to healthy controls." (PMID 39273664, 2024). "In 2022, IL-10 was discovered to be increased in patients with Hashimoto's thyroiditis and SSc, indicating its significance as an indicator of Breg cells’ functionality." (PMID 38431707, 2024). "In the first, peripheral blood TIM-1+ IL-10+ B cells from patients with Graves’ disease and Hashimoto’s thyroiditis were found to be elevated compared to healthy donors." (PMID 28103916, 2017). "One pathway is through a common inflammatory pathway involving factors such as interleukin-6 (IL-6), IL‐12, IL‐10 and tumor necrosis factor that were shown to be significantly higher in women with autoimmune hypothyroidism and euthyroid TAI+ women compared to TAI− controls." (PMID 39888679, 2025). "In individuals with Hashimoto's thyroiditis, there was a significant decrease in the level of CD19+CD24hiCD38hi B cell subsets (B cell populations known for producing IL-10) compared to healthy controls." (PMID 38728262, 2024). "In one study, levels of serum interleukin‐6 (IL‐6), tumor necrosis factor‐α, IL‐12, IL‐10, and IR (HOMA‐index) were investigated in women with Hashimoto’s disease, in euthyroid women with TAI and a control group." (PMID 35195084, 2022). "Cytometric Bead Array (CBA) analysis of pro and anti-inflammatory cytokines (IFN-gamma, IL-2, IL-6, IL-17 A, TNF-alpha and IL-4, IL-10) was done in 15 PTC irrespective of Lymphocytic Thyroiditis (LT) and 16 Hashimoto’s Thyroiditis (HT) cases." (PMID 37563607, 2023). "The proinflammatory cytokine concentrations of IL-8, IL-10, IL-1B, and TNF-α were found to be significantly increased in patients with Hashimoto’s disease, who have anti-thyroid peroxidase antibodies and/or anti-thyroglobulin antibodies as compared to age- and sex-matched controls." (PMID 37241088, 2023). "However, in the present study, the IL-12 was not significantly changed in patients with Hashimoto’s disease as compared to IL-10, which was also increased." (PMID 37241088, 2023).
hypertriglyceridemia (15 papers, 2013 to 2026). A laboratory test result indicating elevated triglyceride concentration in the blood. "Specifically, IL-10 was found to be necessary for preventing hypertriglyceridemia and mitigating adverse cardiac effects, such as impaired glucose oxidation, ectopic lipid accumulation (cardiac steatosis), and ventricular stretching." (PMID 41563955, 2026). "Together, our data suggest that fluoxetine protects from impairment of glucose oxidation in the septic heart and cardiac ectopic lipid accumulation, and this is dependent on IL-10 protection against hypertriglyceridemia." (PMID 39951524, 2025). "Together, our data suggest that fluoxetine-mediated effects on lipid uptake and protection from hypertriglyceridemia are dependent on IL-10." (PMID 39951524, 2025). "Obese children with hypertriglyceridemia also presented decreased IL-10 expression in their serum and adipose tissue." (PMID 38674931, 2024). "This, indicated a protective effect of IL-10 on lipid metabolic disorders, especially hypertriglyceridemia." (PMID 30486837, 2018). "In the present study, we observed that childhood obesity with hypertriglyceridemia were accompanied by a predominant inflammatory state with a decrease of IL-10 expression in SAT." (PMID 29895283, 2018). "Adipose IL-10 and STAT3 mRNA expression and serum IL-10 reduced in obese children with hypertriglyceridemia and in HFD obese rats." (PMID 29895283, 2018). "Thus, IL-10 in adipose tissue and circulation is down-regulated in obese children with hypertriglyceridemia." (PMID 29895283, 2018). "However, when compared with the non-obese and the obese without hypertriglyceridemia group, IL-10 mRNA expression in AT and serum IL-10 levels were lower in obese children with hypertriglyceridemia." (PMID 29895283, 2018). "This study aims to evaluate interleukin-10 (IL-10) in childhood obesity with hypertriglyceridemia." (PMID 29895283, 2018). "Second, hypertriglyceridemia induces the release of more inflammatory cytokines such as interleukin 6 and tumor necrosis factor alpha and reduces the release of anti-inflammatory cytokines such as interleukin 10, which may create a cellular environment conducive to neoplasia." (PMID 32967679, 2020). "IL-10 expression and its downstream JAK-STAT pathway are down-regulated in obese children with hypertriglyceridemia and in HFD obese rats." (PMID 29895283, 2018). "By contrast, increased lipid uptake and protection from hypertriglyceridemia is not necessary for the fluoxetine-mediated effects on IL-10 during infection." (PMID 39951524, 2025). "The Western diet has been suggested to weaken these IL-10-mediated beneficial effects, as IL-10 expression and the downstream JAK-STAT pathway (that is, STAT3) were reduced in serum and adipose tissue of 62 obese children with hypertriglyceridemia and in high-fat diet-induced obese rats." (PMID 37509654, 2023). "We highlight the decrease of IL-10 expression and its downstream JAK-STAT pathway in obese children with hypertriglyceridemia and in HFD obese rats, which indicated that IL-10 might have a protective effect on the lipid metabolic disorders, particularly hypertriglyceridemia." (PMID 29895283, 2018). "However, we innovatively demonstrated that obese children with hypertriglyceridemia showed lower adipose and serum IL-10 compared to obese children without hypertriglyceridemia and non-obese children." (PMID 29895283, 2018). "Furthermore, Matia-García and coworkers recently reported that young obese subjects with hypertriglyceridemia exhibit low-grade systemic inflammation characterized by increasing levels of C-reactive protein (CRP) and IL-6, accompanied by reduced IL-10 serum concentration." (PMID 29675435, 2018).
hypertriglyceridemia (continued). "Investigating the involvement of IL-6 and IL-10 in the activation of STAT3 and NF-κB pathways and in the regulation of endocytosis via GSK3β inhibition or actin filament rearrangements could provide a deeper understanding of the increased BBB permeability seen in hypertriglyceridemia." (PMID 36882782, 2023).
macrophage activation syndrome (15 papers, 2016 to 2025). A complication of rheumatic disease that is caused by excessive activation and uncontrolled proliferation of T lymphocytes and well-differentiated macrophages. "IL-10 levels were significantly lower in patients with macrophage activation syndrome (MAS) than in those with infection-associated HLH (IAHS) and malignancy-associated HLH (MAHS) (P = 0.033, P = 0.012)." (PMID 34348761, 2021). "The hyperinflammatory phase can be identified by an elevated IFN-γ/IL-10 ratio or significantly increased ferritin levels indicating macrophage activation syndrome (MAS)." (PMID 40806563, 2025). "As a result, infection in humans and in animal models leads to a macrophage activation syndrome (MAS) where severity is related to high serum levels of IFNγ, IL-10, IL-12, and ferritin." (PMID 29686681, 2018).
oral cancer (15 papers, 2012 to 2024). "Both present and previous studies showed that the IL-10 rs1800896 gene polymorphism increased the oral cancer risk." (PMID 37077342, 2023). "Stratified analysis was successfully used to relieve moderate heterogeneity bias in the IL-10–1082A > G polymorphism analysis within the Asian population and the oral cancer group, suggesting that ethnicity and cancer location may influence heterogeneity." (PMID 26612133, 2015). "Among a cohort of 80 oral leukoplakias evaluated by IHC for immunomodulatory mediators, increased expression of HLA-G/E, IL10, TGFβ2/3 was noted when compared with oral carcinoma samples." (PMID 36860910, 2021). "Following this, we found that the levels of TNF-α and IL-10, a well-known biomarker for oral cancer, were significantly augmented in the control group; however, GSK343 treatment modulated these inflammatory players’ release in a concentration-dependent manner, counteracting inflammation." (PMID 39204206, 2024). "IL-10 had also been found to be involved in the M2 macrophage polarization process in oral cancer." (PMID 39073672, 2024). "They reported that the IL-10 rs1800896 polymorphism increased the risk of oral cancers, including non-SCC, in both dominant and recessive genetic models." (PMID 37077342, 2023). "In this study, the immunological status of oral cancer patients was characterized by looking at their lymphocyte subsets, and the levels of IL-10 and TGF-β with the hypothesis that OSCC patients would have a compromised immune system with an increased presence of Tregs and levels of IL-10 and TGF-β." (PMID 25153698, 2014). "Multivariate analysis of the influence of HPV 16/18 expression and IL-10 mRNA expression on overall survival (OS) and relapse free survival (RFS) in oral cancer patients." (PMID 23118878, 2012).
atrial fibrillation (14 papers, 2017 to 2025). A disorder characterized by an electrocardiographic finding of a supraventricular arrhythmia characterized by the replacement of consistent P waves by rapid oscillations or fibrillatory waves that vary in size, shape and timing and are accompanied by an irregular ventricular response. "In fact, a recent systematic review comprising eight randomized controlled trials could show that six (75%) studies were found to be in favor of improvement in postoperative VIS, ICU stay, postoperative atrial fibrillation, IL-10 levels, or fewer cardiac adverse events." (PMID 39202041, 2024). "Plasma levels of inflammatory cytokines of IL‐2, IL‐4, IL‐10, TNF, and IFN‐γ were reduced upon rivaroxaban treatment compared to warfarin in atrial fibrillation patients, with levels still slightly higher than controls." (PMID 40292918, 2025). "In the atrial fibrillation group, the ability of mDCs to stimulate T cells to secrete IL-2 and IFN-γ was significantly higher, and the ability to secrete IL-10 was significantly lower compared with the control group (P < 0.05)." (PMID 35600045, 2022). "Conversely, lower levels of CCL3, IL-12, IL-5, IL-10, IL-13 were observed in the ZIKV-infected patient with atrial fibrillation as compared to the healthy controls." (PMID 29370812, 2018). "After α interferon upregulated PD-L1 expression in cells, the ability of mDCs to stimulate T cells to secrete IL-2, IL-10, and IFN-γ cytokines was reversed in patients in the atrial fibrillation group, and the differences compared with the control group were not statistically significant (P > 0.05)." (PMID 35600045, 2022).
autoimmune thyroid disease (14 papers, 2015 to 2025). Inflammatory disease of the thyroid gland due to autoimmune responses leading to lymphocytic infiltration of the gland. "Cytotoxic T-lymphocyte associated protein 4 (CTLA-4) inhibition worsened autoimmune thyroiditis in mice via the production of interleukin (IL)-2, interferon gamma, IL-10, and IL-13 cytokines." (PMID 34234669, 2021). "Indeed, a recent meta-analysis of the rs1800896 polymorphism revealed a significant association between autoimmune thyroid disease and the −1082 G allele and the GG + GA genotype of the IL10 gene." (PMID 37626843, 2023). "Subfertile women with autoimmune thyroid disease usually express increased levels of IFNγ from pro-inflammatory Th1 immune cells, along with lower IL-4 and IL-10 from Th2 immune cells compared with control patients without antithyroid antibodies." (PMID 35351031, 2022). "Increased IL-10 expression has been reported in autoimmune thyroid diseases, suggesting that anti-inflammatory responses may occur simultaneously via IL10RB, DUSP1, DUSP2, and RGS1 in GD." (PMID 40710355, 2025). "In patients with autoimmune thyroid disease (AITD), IL-10 mRNA expression was found to increase significantly, decreasing as the autoimmune process subsided." (PMID 39104791, 2024). "Our previous study explored the quantitative changes in the CD19+CD1dhiCD5+ B cell subset in the iodine-induced autoimmune thyroiditis of NOD.H-2h4 mice and found a significant decrease in this B cell subset and reduced IL-10 mRNA expression in mouse splenocytes." (PMID 29259988, 2017). "Compared to women who test negative for thyroid antibodies, women with autoimmune thyroid disease and reduced fertility typically exhibit elevated levels of pro-inflammatory immune cytokines from Th-1 cells (such as IFN-γ), along with decreased levels of IL-4 and IL-10 produced by Th-2 immune cells." (PMID 38298186, 2023).
chorioamnionitis (14 papers, 2005 to 2025). A morphologic finding indicating inflammation of the fetal sac membranes. "In placental tissue, reduced levels of the anti‐inflammatory cytokine IL‐10 are associated with both chorioamnionitis‐induced preterm labor and term labor." (PMID 41369322, 2025). "To investigate the effect of BD2 on the amniotic membrane in patients with chorioamnionitis, we compared the levels of inflammatory cytokines, including IL-6 and IL-1β, and anti-inflammatory cytokines such as IL-10 between the patient and normal groups." (PMID 40076749, 2025). "A further limitation was that we were unable to assay other inflammatory proteins that are generally considered to be the most relevant in intra-amniotic infections, such as IL-1β, IL-10, IL-18, and MMPs, because of limited research funding available." (PMID 29979758, 2018). "Our data support the role of IL10, MBL2 and TNFRSF6 variants in determining the risk of histologic chorioamnionitis." (PMID 15723707, 2005). "Treatment with IL-10 for intra-amniotic infections in animal studies reduced uterine contractions." (PMID 27486805, 2016). "In chorioamnionitis, diminished IL-10 levels may provide an ineffective counter regulatory response to elevated maternal prostaglandin stimulated by the pro-inflammatory cytokines IL-1, IL-6 and TNF." (PMID 15723707, 2005). "Our finding that the carriage of the IL10 ATA haplotype is more common in women with histologic chorioamnionitis suggests that this haplotype may be important in the pathogenesis of histologic chorioamnionitis and subsequent PTB." (PMID 15723707, 2005). "Multiple clinical and animal studies have helped to better characterise this pathological inflammatory response in chorioamnionitis, demonstrating the presence of elevated levels of interleukins (IL)−1β, IL-6, IL8, IL-10 in amniotic fluid." (PMID 40464837, 2025). "In contrast, targeted analysis of IL8, IL10, IL18, TNFα in maternal plasma of the 2 d Sterile Chorioamnionitis Group animals improved predictive value with a mean AUC of 0.73 (95% CI 0.39–1) Sensitivity 100%, Specificity 71%, PPV 0.82, NPV 1.0." (PMID 40464837, 2025). "We performed targeted analyses utilising Random Forest Algorithm of the same eight cfRNA targets (IL1α, IL1β, IL6, IL8, IL10, IL18, CD14, TNFα) used in the chorioamnionitis study." (PMID 40464837, 2025). "The differences in genotype distribution for IL10 and MBL2 may be of biologic importance in the pathogenesis of histologic chorioamnionitis." (PMID 15723707, 2005). "Interestingly, a decrease in the anti-inflammatory cytokine, IL-10, coincides with non-infectious and non-inflammatory cytokine-mediated clinical chorioamnionitis at term, similar to the decrease in anti-inflammatory epoxy PUFA." (PMID 33117385, 2020). "In preterm women without histologic chorioamnionitis frequencies for the IL10-1082A/-819T/-592A (ATA) haplotype, MBL2 codon 54Asp (the MBL 'B' allele), TNFRSF6-1377A/-670G (AG) haplotype and TGFB1-800G/-509T (GT) homozygosity were similar to reported Caucasian controls." (PMID 15723707, 2005).
colorectal tumors (14 papers, 2006 to 2025). "The IL10−/− mouse does not produce the anti-inflammatory cytokine, IL-10, in the colon, and thus experiences chronic inflammation; the compound AOM induces DNA damage in the colon, leading to the development of colorectal tumors in IL-10-null mice." (PMID 37765299, 2023). "For example, in the IL-10-/- mice, COX2, which is overexpressed by myofibroblasts, is strongly increased and associated with the ulcerated regions of colorectal tumors." (PMID 33916891, 2021). "This was in agreement with a study that showed increased frequencies of FoxP3− Treg cells in colorectal tumors, which were even more suppressive than FoxP3+ Treg cells and produced IL-10 and TGF-β." (PMID 27014625, 2016). "Il10−/− mice developed an average of 0.8 colorectal tumors/mouse while Il10−/−; Myd88−/− mice were devoid of neoplastic lesions." (PMID 19551144, 2009). "Oral administration of IL-10 reduced the number of polyps/+ model ApcMin, whereas T cell-restricted ablation of IL-10 increased the number of polyps by promoting the accumulation of microbes and eosinophils in colorectal tumors." (PMID 35884974, 2022). "Furthermore, disruption of MyD88 signaling, a key integrator of multiple TLRs prevented the development of colorectal tumors in Il10−/− mice." (PMID 19551144, 2009). "Expression of CD155 was associated with an M2-like phenotype and a higher expression of interleukin (IL)-10 and transforming growth factor (TGF)-β, as well as with colorectal tumor stages III/IV and with a shorter survival." (PMID 40274631, 2025). "In the AOM/DSS-induced orthotopic CRC model, KGM-PTX/CSM significantly inhibited colorectal tumor growth, improved survival rates, and suppressed inflammatory cytokine expression (TNF-α, IL-1β, IL-6, and IL-10) in serum and colorectal tissues." (PMID 40528838, 2025). "Aggravation of colorectal tumors; induction of inflammatory cytokines and pathways (TNF-α, IL-1β, IL-6, IL-10)." (PMID 35893902, 2022). "By contrast, mice lacking the anti-inflammatory cytokine IL-10 spontaneously developed colorectal tumors after colitis." (PMID 33916891, 2021). "Moreover, IL-17 secreting CD4+ T cells infiltrated in colorectal tumors can coproduce TNF-α and IL-10." (PMID 33327620, 2020). "Additionally, AOM-treated Il10−/−; Myd88−/− mice failed to develop colorectal tumors, indicating that bacterial signaling through the TLR/MyD88 system is required for development of CAC." (PMID 19551144, 2009). "In contrast, 53% of DKO mice developed large bowel tumors under SPF conditions, but none of the MSH2loxP/loxP Vil‐cre mice and only one out of 12 IL‐10−/− mice." (PMID 32350866, 2020).